DOK1 (docking protein 1)
Diseases named in the same sentence as DOK1 in open-access papers (continued):
Sharing a sentence is not in itself a finding about the gene and the disease.
tumor (14 papers, 2011 to 2024). "The downstream of tyrosine kinase 1gene (DOK1) has emerged as a newly identified tumor suppressor gene that encodes a multi-domain adapter protein and acts as a negative regulator of signaling pathways involved in several cellular functions." (PMID 24809689, 2014). "To assess how Dok-1/-2 deficiency enhances tumor growth but Dok-3 deficiency induces malignant conversion of benign tumors, we first evaluated expression levels of the Dok family genes in tumor epithelial cells of Apc mice." (PMID 36970719, 2022). "In addition, on a 129S1/SvImj genetic background, single, double, or triple deficiency in Dok1/2/3 genes causes lung cancer in mice, together indicating tumor suppressor function." (PMID 36970719, 2022). "We made a subcutaneous B16-hgp100 tumor injection and 10 days after we performed an adoptive cell transfer of WT and Dok1/Dok2 DKO CD8+ T cells." (PMID 38956389, 2024). "This is of cardinal importance because of the vague DOK1 role as tumor suppressor or tumor promoting in various contexts 5-10." (PMID 39513127, 2024). "RB1 is a well-known tumour suppressor protein (pRb), and DOK1 (docking protein 1) is also a tumour suppressor, which shows repressed expression in many human tumours owing to hypermethylation of its promotor region." (PMID 32616892, 2020). "Herein, RASSF1A and DOK1 methylation levels showed a gradual increase according to the progression of the disease, with significantly higher levels in tumor tissues." (PMID 27078152, 2016). "The Ras association domain family 1A (RASSF1A) and downstream of tyrosine kinases 1 (DOK1) are tumor suppressor genes frequently silenced through epigenetic mechanism in a variety of human malignancies." (PMID 27078152, 2016). "Together, these results suggest a novel mechanism of action of BRK in the promotion of tumor formation, which involves the targeting of tumor suppressor Dok1 for degradation through the ubiquitin proteasomal pathway." (PMID 24523872, 2014). "Dok1 is a tumor suppressor and several studies have concurred that the overexpression of Dok1 suppresses cell proliferation and migration." (PMID 24523872, 2014). "Dok1 is a tumor suppressor and there are several potential mechanisms that account for the inactivation of tumor suppressors in cancer including those pertaining to the regulation of gene expression and post-translational events targeting protein stability." (PMID 24523872, 2014). "Since Dok1 is a tumor suppressor and we observed a dramatic difference between the effects of BRK-WT and BRK-Y447F on Dok1 expression, we evaluated the growth rates of the stable cell lines." (PMID 24523872, 2014). "In a recent proteomic study, downstream of tyrosine kinase 1 (Dok1), a tumor suppressor, was identified as a potential substrate of BRK." (PMID 24523872, 2014). "Since Dok1 has been described as a candidate tumor suppressor and work from our laboratory and others indicate that BRK has oncogenic properties, we opted to investigate the functional link between BRK and Dok1." (PMID 24523872, 2014). "Dok1 was functionally identified as a tumor suppressor based on several studies that demonstrated an antagonizing role of the adaptor protein towards p210bcr-abl-mediated cell transformation in vivo." (PMID 24523872, 2014). "We have demonstrated the tumor promoting role of DOK1 in ccRCC." (PMID 39513119, 2024). "Docking protein 1 (DOK1) is a putative tumor suppressor gene; however, its role in ccRCC remains unclear." (PMID 39513119, 2024). "Interestingly, the loss of Dok-1/-2, the homologs of Dok-3, did not significantly affect malignant progression but rather enhanced tumor growth in Apc mice, indicating distinct roles of Dok-3 and Dok-1/-2." (PMID 36970719, 2022). "A tumor suppressor gene, and methylation level of DOK1 is inversely related with gene expression." (PMID 34660653, 2021).
tumor (continued). "Thus, DOK1 emerged as a tumor suppressor frequently altered in a variety of human cancers, making it a potential marker and therapeutic target in cancer control." (PMID 24809689, 2014). "We then investigated the role of DOK1 and DOK2 in physiology, TCR signaling and activation of naïve and primed CD8+ T cells and cytotoxic capacity against tumor cells." (PMID 38956389, 2024). "First, although the compelling evidence of DOK1's involvement in the PI3K/AKT/GSK3β signaling pathway in ccRCC, the broader network of interactions within the tumor microenvironment (TME) remains elusive." (PMID 39513127, 2024). "In summary, our data show the deregulation of DOK1 gene expression by EBV and provide novel insights into the regulation of the DOK1 tumor suppressor in viral-related carcinogenesis." (PMID 24809689, 2014). "Two of these, CBX7 and EGR1, have well-described tumor suppressor functions, and recently DOK4 family members (DOK1, DOK2, and DOK3) were identified as lung tumor suppressors." (PMID 21375733, 2011). "Building on these results, we hypothesized that DOK1 and DOK2 invalidation in CD8+ T cells may be a promising approach to improve their anti-tumor functions and thus subsequent immunotherapy." (PMID 38956389, 2024). "Since we recently reported that constitutively active BRK (BRK-Y447F) promotes tumor formation, we examined whether BRK-Y447F, like oncogenic Src, could downregulate endogenous Dok1." (PMID 24523872, 2014). "The downstream of tyrosine kinase (DOK) family is composed of seven members, DOK1 to DOK7, and some of them have the effects on the negative regulation of tumor signaling pathways." (PMID 33552156, 2021). "Mean rates of methylation in RASSF1A and DOK1 were 16.2% and 12.0% in non-cirrhotic, 26.1% and 19.6% in cirrhotic, and 59.1% and 56.0% in HCC tissues, respectively, showing a gradual increase according to the progression of the disease, with significantly higher levels in tumor tissues." (PMID 27078152, 2016).
cancer (8 papers, 2014 to 2025). A tumor composed of atypical neoplastic, often pleomorphic cells that invade other tissues. "Our results confirm that hypermethylation of RASSF1A and DOK1 contributes to hepatocarcinogenesis and is an early event in cancer development, likely associated to clinical characteristics as well as major risk factors." (PMID 27078152, 2016). "Here, we show that dynamic ITGB1 phosphorylation facilitates the recruitment of a proinvasive Dok1 complex to support invadopodia formation, cancer invasion and metastatic dissemination." (PMID 40419795, 2025). "To understand how DOK1 and DOK2 regulate CD8+ T cell activity and especially their cytotoxic function against cancer cells, we crossed Dok1/Dok2 DKO mice with pmel-1 TCR transgenic mice." (PMID 38956389, 2024). "To further understand how DOK1 and DOK2 regulate CD8+ T cell activity and especially their cytotoxic function against cancer cells, we crossed Dok1/Dok2 DKO mice with pmel-1 TCR transgenic mice." (PMID 38956389, 2024). "The DOK1 gene is a newly identified tumor suppressor gene with altered expression via hypermethylation of its promoter in a variety of human cancers, including head and neck, lung, gastric and others." (PMID 24809689, 2014). "We thank to Dr. Ryuji Kobayashi, MD Anderson cancer centre, University of Texas, Austin, USA, for providing us with the anti-Dok1 antibody and Dr. Bakary S. Scylla, Lyon France, for providing us with the GFP-Dok1 plasmid." (PMID 24523872, 2014). "Expression of LMP1 alone in human cancer B-cells was sufficient to efficiently inhibit DOK1 transcription by promoting the formation of a transcriptional repressor complex containing E2F1, pRB, and the DNA methyl-transferase DNMT1." (PMID 24809689, 2014). "It provides novel insights into the regulation of DOK1 in viral-related carcinogenesis, and could define it as a potential cancer biomarker and an attractive target for epigenetic-based therapy." (PMID 24809689, 2014). "A recent study has provided evidence that DOK1 inactivation also occurs in virus-induced cancers." (PMID 24809689, 2014). "Nck adaptors in interaction with Dok1 induce podosome biogenesis and ECM degradation facilitating cancer cell invasion, and therefore a bona fide target of cancer therapy." (PMID 31638742, 2019). "We hypothesized that depletion of intracellular inhibition checkpoint DOK1 and DOK2 could improve CD8+ T-cell based cancer therapies." (PMID 38956389, 2024). "Similarly, DOK1 mRNA and protein levels were strongly down-regulated by EBV in three cancers B-cell lines (RPMI, BJAB and Louckes) infected by EBV, as well as in EBV-immortalized lymphoblastoid cells lines (LCLs)." (PMID 24809689, 2014).
infection (6 papers, 2014 to 2024). The state of being infected such as from the introduction of a foreign agent such as serum, vaccine, antigenic substance or organism. "Based on our previous results that showed the down-regulation of DOK1 expression in BL cell-lines, we evaluate whether this event was linked to infection with EBV, a key risk factor for this malignancy." (PMID 24809689, 2014). "Consistent with the IP experiment, RasGAP co-localization with Dok-1 was increased during infection of serum pre-opsonized Schu S4." (PMID 29632532, 2018). "Increased Dok-1 phosphorylation was observed consistently between 1 and 5 min following infection with pre-opsonized bacteria, depending on the donor." (PMID 29632532, 2018). "The expression of EBV genes EBNA1 and LMP1, as well as DOK1 was determined by real-time PCR and western blot at different time points post-infection." (PMID 24809689, 2014). "EBV infection resulted in a strong reduction of DOK1 mRNA and protein levels, which was evident at 16 hours post-infection." (PMID 24809689, 2014). "Association of RasGAP with Dok-1 was increased upon infection by pre-opsonized Schu S4 compared to that of non-opsonized bacteria." (PMID 29632532, 2018). "Finally, the events occurring at DOK1 promoter were determined at early stages post-infection with EBV." (PMID 24809689, 2014). "In contrast to wild-type GFP-EBV, EBVΔLMP1 infection in primary B cells and in RPMI cells did not significantly decrease DOK1 mRNA or protein levels." (PMID 24809689, 2014).
bacterial infection (1 paper, 2016). "Most importantly, downregulation of Dok1 gene expression in human alveolar macrophages after P. aeruginosa infection in vitro, indicates its direct involvement in this bacterial infection." (PMID 27169516, 2016).
benign tumors (1 paper, 2022). "However, the role of Dok-1/-2/-3 in malignant conversion of benign tumors remains unknown." (PMID 36970719, 2022).
DOK1 also shares sentences with these, for which no sentence is quoted: lung carcinoma (3 papers); head and neck cancer (2); lung adenocarcinoma (2); allergic disease (1); colorectal cancer (1); eosinophilia (1); esophageal motility disorder (1); monocytic leukemia (1); prediabetes (1); viral infection (1).